KRAS (KRas proto-oncogene, GTPase)
Diseases named in the same sentence as KRAS in open-access papers (continued):
Sharing a sentence is not in itself a finding about the gene and the disease.
endometrial adenocarcinoma (2 papers, 2016 to 2021). "Mutations affecting the KRAS/GTP interface and those targeting the CTNNB1 interfaces with FBXW11 or BTCR are largely mutually exclusive when considering all cancer types, and particularly for endometrial adenocarcinoma, where both mutations are common." (PMID 27698488, 2016).
esophageal melanoma (2 papers, 2015 to 2021). A melanoma affecting the esophageal wall. "Because the data are controversial due to the fact that BRAF/KRAS/KIT coexisting mutations were previously reported, particularly in primary esophageal melanomas, we attempted to explore the possible interaction of these three genes." (PMID 34769348, 2021).
esophageal tumors (2 papers, 2016 to 2021). "The distribution of KRAS mutation was similar in gastric and esophageal tumours, 3 (4.3%) and 4 (4.0%) respectively." (PMID 26844548, 2016). "In fact, 80% of KRAS alterations in esophageal tumors were amplifications, which correlated with the TCGA dataset." (PMID 33889297, 2021).
fibroma (2 papers, 2022 to 2023). A non-metastasizing neoplasm arising from the fibrous tissue. "A nonossifying fibroma (NOF) of the bone identified a mosaic pathogenic variant in KRAS p.Gly13Asp (c.38G > A, NM_033360.3) with 32.9% VAF by exome sequencing as was previously reported." (PMID 37154160, 2023). "Frequently, prominent foamy histiocytes are found in non-ossifying fibromas; however, these lesions present with characteristic radiologic findings and KRAS mutation." (PMID 36555836, 2022).
folliculitis (2 papers, 2020 to 2021). Inflammation of the hair follicles. "We demonstrated that ECOG PS <2, conduct of metastatic surgical treatment, and occurrence of maximum grade xerosis or folliculitis were predictive factors of cetuximab efficacy in KRAS wt mCRC patients." (PMID 33347495, 2020). "ECOG PS <2, surgical treatment performed, and maximum grade xerosis or folliculitis developed were predictive factors of cetuximab efficacy on KRAS wt mCRC patients." (PMID 33347495, 2020).
Gastric Metaplasia (2 papers, 2021 to 2023). Intestinal metaplasia of the gastric mucosa is an intermediate precancerous gastric lesion in the gastric cancer cascade from chronic gastritis and atrophy to dysplasia and adenocarcinoma. "Here, we found that the combination of sustained Hp infection and active KRAS expression has a unique impact on the development of gastric metaplasia that is not observed with either individual parameter." (PMID 33310760, 2021). "However, only 4/7 KRAS− mice and 5/8 KRAS+ mice were colonized, and median titers were three to four logs lower than titers of PMSS1, demonstrating that 7.13 is overall not a robust colonizer of mice, regardless of gastric metaplasia status." (PMID 36598261, 2023).
germinoma (2 papers, 2016 to 2025). A malignant germ cell tumor arising in the central nervous system. "Recurrent somatic mutations in the KIT/RAS/MAPK pathways and AKT/mTOR pathways have been well documented in intracranial GCTs, with KIT/KRAS/MAPK alterations known to be enriched in germinomas." (PMID 39959669, 2025).
glioneuronal tumor (2 papers, 2020 to 2022). "KRAS Q61H mutated case had histology of low-grade glioneuronal tumor (LGNT), and the patient was observed only after partial resection." (PMID 36163281, 2022).
Gorham-Stout disease (2 papers, 2023 to 2024). Gorham-Stout disease (GSD) is a rare disease of massive osteolysis associated with proliferation and dilation of lymphatic vessels. "The efficacy of trametinib, a MEK1/2 inhibitor, has been demonstrated in a single patient case of RAS-related CLAs and in a KRAS-driven mouse model of Gorham-Stout disease." (PMID 37154160, 2023). "Gorham-Stout disease (GSD) has also been studied in the iLECKRAS mouse model using Prox1-CreERT2 to drive LEC-specific expression of KRAS (G12D), after an activating somatic variant in KRAS (G12V) was identified in one individual with GSD." (PMID 38618951, 2024). "Nonetheless, in combination with previous work in a KRAS-driven mouse model of Gorham-Stout disease, our data suggest that use of a MEK inhibitor for the treatment of lymphatic anomalies due to pathogenic variants in the RAS/MAPK pathway should be systematically evaluated in future trials." (PMID 37154160, 2023).
hyperlipidaemia (2 papers, 2023 to 2024). "This study showed that the activation of the ANGPTL4/IL-8/NOX4 axis and KRAS is essential for hyperlipidemia-promoted metastasis." (PMID 37649607, 2023). "We also showed for the first time that combining antioxidants and inhibition of KRAS can improve therapeutic efficacy in the metastasis of cetuximab-resistant CRC with hyperlipidemia status." (PMID 37649607, 2023). "It would be interesting to pursue whether hyperlipidemia induces the formation of exosome-containing mutant KRAS to regulate IL-8 expression, CRC metastasis, and the recruitment of macrophages, and this must be investigated further." (PMID 37649607, 2023). "In addition, the effects of antioxidants and depletion of IL-8 and KRAS on the correlation between ROS production and hyperlipidemia-promoted CRC metastasis were also clarified." (PMID 37649607, 2023). "The hyperlipidemia-triggered metastatic ability of CRC cells under treatments of antioxidants, statin, and cetuximab or knockdown of IL-8, KRAS, and EGFR was evaluated in vitro and in vivo." (PMID 37649607, 2023).
hyperparathyroidism (2 papers, 2023). Hyperfunction of the parathyroid glands resulting in the overproduction of parathyroid hormone. "Moreover, KRAS mutations are emerging as major players in a variety of non-neoplastic malformative vascular lesions and benign tumors including subsets of capillary hemangioma, non-ossifying fibroma of bone, brown tumor of hyperparathyroidism and others." (PMID 36752878, 2023).
hypertrophic cardiomyopathy (2 papers, 2013 to 2019). A condition in which the myocardium is hypertrophied without an obvious cause. "We describe a patient with NS and rapidly progressive hypertrophic cardiomyopathy with lethal outcome, in whom we identified a novel mutation in the KRAS gene." (PMID 24382853, 2013).
Hypoglycemia (2 papers, 2019 to 2020). A decreased concentration of glucose in the blood. "While hypoxia increases the expression of nonmutated KRAS through protein kinase c-Src activation, hypoglycemia favors the expression of several KRAS mutants, with the G12D mutated protein being the most commonly expressed in cancer cells." (PMID 31600993, 2019).
intestinal type adenocarcinoma (2 papers, 2021 to 2025). An adenocarcinoma arising from epithelium which has undergone intestinal metaplasia.
invasive breast carcinoma (2 papers, 2024). A carcinoma that infiltrates the breast parenchyma. "Additionally, although recent evidence has reported a role for overexpression of wild-type KRAS, HRAS, or NRAS in different carcinomas, including invasive breast cancers, a driver role in their wild-type form for tumorigenesis in in vivo models has not yet been demonstrated." (PMID 38987766, 2024).
keloid (2 papers, 2017 to 2021). An irregularly shaped, elevated mark on the skin caused by deposits of excessive amounts of collagen during wound healing. "Meanwhile, the GSVA results presented 10 downregulated gene sets in keloid tissue compared with normal skin, e.g., xenobiotic metabolism, UV response up, KRAS signaling up, and adipogenesis." (PMID 33860039, 2021).
Langerhans cell sarcoma (2 papers, 2018 to 2025). A neoplastic proliferation of Langerhans cells with overtly malignant cytologic features. "Here, we described a rare occurrence of a low grade FL transdifferentiating into a Langerhans cell sarcoma (LCS) with acquisition of KRAS mutation." (PMID 30322385, 2018). "Finally, histiocytes and B cells harboring the same KRAS mutation were identified in the unifocal Langerhans cell sarcoma lesion of the only patient without circulating mutated cells." (PMID 40453139, 2025).
lung disease (2 papers, 2016 to 2022). "Clinical uses for KRAS mutation analysis in lung disease include its use as a diagnostic indicator for cancer in sputum and BALF samples." (PMID 36552956, 2022).
lung NETs (2 papers, 2022 to 2025).
lymph node tumor (2 papers, 2010 to 2022). "In sample 0940, the KRAS/PIK3CA mutation decreased by almost 1/2 in the lymph node tumor compared to the primary." (PMID 20233444, 2010). "On the other hand, if the PIK3CA/KRAS ratio were the same in the primary and lymph node tumor, then the PIK3CA mutation frequency would have been .08, which is still detectable with this technology." (PMID 20233444, 2010). "Surprisingly, after analysing and comparing the impractical KRAS (those with metachronous and negative lymph node tumours) with KRAS mutated or KRAS wild-type patients, the difference in terms of HRFS, DFS and OS sharply increased over the others." (PMID 35326950, 2022).
lymphangiectasia (2 papers, 2022 to 2023). "Additionally, improvement with sirolimus has been reported for an individual with lymphangiectasia and overgrowth due to KRAS p.Gly12Asp, though others have reported no improvement." (PMID 37154160, 2023).
malignant phyllodes tumor (2 papers, 2022 to 2023). A phyllodes tumor with sarcomatous stroma. "PIK3CA/KRAS and HRAS alterations have already been reported in borderline and malignant phyllodes tumors." (PMID 37240386, 2023).
mesenchymal tumors (2 papers, 2014 to 2021). "The frequency of somatic mutations in the KRAS and BRAF genes varies in tumors of these two subtypes; but it is significantly higher in mesenchymal tumors, and 3 out of 4 BRAF-V600E mutations were discovered in these tumors." (PMID 25157365, 2014).
metastatic prostate carcinoma (2 papers, 2021 to 2024). A carcinoma that arises from the prostate gland and has spread to other anatomic sites. "Although the KRAS gene is not commonly aberrant in metastatic prostate cancer (7%), deregulation of RAS proteins signalling has been reported and has tumour-promoting activity." (PMID 39239510, 2024).
mucinous cystadenocarcinoma (2 papers, 2007 to 2021). An invasive adenocarcinoma characterized by cystic changes and the presence of malignant glandular cells which contain intracytoplasmic mucin. "KRAS mutations, which are typical for mucinous carcinomas of the lung, may also be a mechanism for the development of mucinous cystadenocarcinoma arising from PCMA." (PMID 34397923, 2021).
Myelodysplasia (2 papers, 2020 to 2025). Clonal hematopoietic stem cell disorders characterized by dysplasia (ineffective production) in one or more hematopoietic cell lineages, leading to anemia and cytopenia. "The presence of poor-risk cytogenetic abnormalities, the presence of other mutations in myeloid genes, and the presence of mutations in myelodysplasia-related genes and/or mutations in NRAS/KRAS did not seem to have a significant impact on the EFS and OS." (PMID 40002262, 2025). "However, the presence of adverse risk cytogenetics and mutations in myeloid genes, myelodysplasia-related genes and/or NRAS/KRAS had no impact on the EFS and OS." (PMID 40002262, 2025).
myxoma (2 papers, 2017 to 2025). A benign soft tissue neoplasm characterized by the presence of spindle and stellate cells, lobulated growth pattern, and myxoid stroma formation. "While PRKAR1A, PIK3CA (Q546E) and KRAS mutation (G12V), mutations have been detected in a minority of OMs and GNAS1 mutations are well described in intramuscular myxomas, neither has emerged as a consistent molecular feature of OMs." (PMID 41364259, 2025).
Neonatal sepsis (2 papers, 2021 to 2026). Systemic inflammatory response to infection in newborn babies. "A recent study also reported that KRAS is implicated in the neonatal sepsis based on a comprehensive bioinformatics analysis." (PMID 34804111, 2021).
non-Hodgkin lymphoma (2 papers, 2016 to 2023). Distinct from Hodgkin lymphoma both morphologically and biologically, non-Hodgkin lymphoma (NHL) is characterized by the absence of Reed-Sternberg cells, can occur at any age, and usually presents as a localized or generalized lymphadenopathy associated with fever and weight loss.
oncocytoma (2 papers, 2017 to 2023). "Furthermore, recent studies suggested that autophagy is required for mitochondrial function, lipid metabolism, growth, and fate of KRASG12D-driven lung tumor, as well as autophagy suppresses progression of KRAS-induced lung tumors to oncocytomas and maintains lipid homeostasis." (PMID 28443025, 2017).
ossifying fibroma (2 papers, 2021 to 2024). A bone benign neoplasm that is located_in the mouth and results_in an overgrowth of gingival tissue due to irritation or trauma. "Non-ossifying fibroma/benign fibrous histiocytoma, KRAS and FGFR1 mutations were confirmed." (PMID 39850815, 2024).
pancreatic diseases (2 papers, 2021). "Finally, KRAS alleles have been assessed by quantitative ddPCR in a large series of patients with PDAC, pre-neoplastic pancreatic cyst and non-neoplastic pancreatic diseases." (PMID 33673558, 2021). "Quantitative ddPCR found average KRAS MAF to be highest in baseline metastatic samples, followed by localized disease, cystic lesions and finally, non-neoplastic pancreatic diseases." (PMID 33673558, 2021). "A study enrolled patients with various pancreatic disorders, including PDA and non-malignant diseases, and detected mutant KRAS in five out of twelve metastatic PDA, compared to a detection rate of 97 % in tumor samples." (PMID 33593396, 2021).
Pancreatoblastoma (2 papers, 2018 to 2024). A rare malignant epithelial neoplasm arising from the pancreas.
pericardial effusion (2 papers, 2012 to 2022). Fluid collection within the pericardial sac, usually due to inflammation. "We found an increased EGFR mutation frequency (27 %) and a decreased KRAS mutation frequency (19 %) in patients with malignant pleural or pericardial effusions." (PMID 22528563, 2012). "Among the 3 actionable alterations with SNVs/indels, 2 (66.7%) (EGFR L861Q and KRAS G12C) had a higher VAF in pericardial effusion compared with PE-cfDNA." (PMID 35646096, 2022). "Among the 6 actionable alterations, EML4-ALK (exon 20: exon 20) fusion, ERBB2 Y772_A755dupYVMA and KRAS G12C showed a consistency of 100% between PE-cfDNA and pericardial effusion." (PMID 35646096, 2022). "Both for EGFR and KRAS the category pleural and pericardial effusions was associated with a difference in mutation frequency compared to primary tumors (EGFR OR = 2.80 (95 % CI 1.22-6.41), p = 0.015; KRAS OR = 0.35 (95 % CI 0.14–0.86), p = 0.022)." (PMID 22528563, 2012). "Among the actionable alterations, MET amplification exhibited the highest population frequency, while EGFR E746_A750delELREA, EGFR T790M, EML4-ALK (exon 20: exon 20) fusion, and KRAS G12C displayed a 100% consistency between the tumor tissue and pericardial effusions." (PMID 35646096, 2022). "Among them, EGFR T790M, EGFR E746_A750delELREA, EGFR L861Q, KRAS G12C, EML4-ALK (exon 18: exon 20) fusion, EML4-ALK (exon 20: exon 20) fusion, and ERBB2 Y772_A755dupYVMA were detected in both pericardial effusion-cfDNA and pericardial effusion-sDNA." (PMID 35646096, 2022).
pneumonitis (2 papers, 2018 to 2024). An inflammatory process affecting the lung parenchyma. "Adagrasib and sotorasib are available for the treatment of KRAS G12C mutations, and they have acceptable pneumonitis rates, which can therefore be a game changer in these patients." (PMID 39062713, 2024). "In the OAK study, patients baseline characteristics include more EGFR KRAS mutation positive and ALK fusion positive patients, those patients who receive previous treatment with tyrosine kinase inhibitor are more likely to experience pneumonitis and lung inflammation." (PMID 30618738, 2018).
rectal NETs (2 papers, 2019 to 2023).
recto-sigmoid cancer (2 papers, 2005 to 2020). "In patients with KRAS mutated recto-sigmoid cancer stage III at diagnosis, high chol:HDL ratio was associated with better survival." (PMID 32594310, 2020). "In 22 patients with KRAS mutated recto-sigmoid cancer stage IV at diagnosis normal chol:HDL ratio was associated with a trend to better survival (p = 0.06)." (PMID 32594310, 2020). "In 13 patients with KRAS mutated recto-sigmoid cancer stage III at diagnosis, we observed better survival in patients with high chol:HDL ratio (p = 0.05)." (PMID 32594310, 2020). "High chol:HDL ratio was significantly associated with KRAS mutated metastatic recto-sigmoid cancers." (PMID 32594310, 2020). "In conclusion, chol:HDL ratio was significantly associated with KRAS mutation in metastatic recto-sigmoid cancers." (PMID 32594310, 2020). "A subgroup of mCRC patients with KRAS mutated recto-sigmoid cancer may benefit from optimal lipid lowering treatment." (PMID 32594310, 2020). "Lipid lowering treatment may be effective in a subset of patients with KRAS mutated metastatic recto-sigmoid cancer." (PMID 32594310, 2020). "In this study in non recto-sigmoid cancers high serum cholesterol was associated with KRAS WT." (PMID 32594310, 2020). "Results of the present study suggest that dysregulated serum lipid profile may be implicated in KRAS mutated signaling pathways in a subset of KRAS mutated metastatic recto-sigmoid cancers, thus leading to the deduction that lipid lowering treatment may be effective in such subset of mCRC patients." (PMID 32594310, 2020). "In recto-sigmoid cancers there was a statistically significant association between high cholesterol:high-density lipoprotein (chol:HDL) ratio and KRAS mutation (OR 2.69, 95% CI 1.1–6.4, p = 0,02)." (PMID 32594310, 2020).
Sepsis (2 papers, 2020 to 2021). Sepsis is defined as life-threatening organ dysfunction caused by a dysregulated host response to infection. "Thus, our results indicate that KRAS may also participate in the progression of septic shock and be regarded as a potential therapeutic target, providing a new enlightenment for sepsis research." (PMID 34804111, 2021).
skin toxicity (2 papers, 2012 to 2025). "For QLQ-C30 global health status, the model yielded a significant difference between these two groups but there were also interactions between baseline global health status score and skin toxicity overall in the PRO analysis set and within the MT KRAS PRO population (data not shown)." (PMID 23020584, 2012).